EMD (emerin)
Diseases named in the same sentence as EMD in open-access papers (continued):
Sharing a sentence is not in itself a finding about the gene and the disease.
ovarian carcinoma (2 papers, 2011 to 2018). A malignant neoplasm originating from the surface ovarian epithelium. "We further speculate that nuclear structural defects as a consequence of the loss of lamin A/C (and also loss of emerin) may be a principal mechanism for the chromosomal numerical instability, and the underlying cause of aneuploidy in ovarian cancer." (PMID 21439080, 2011). "Thus, nearly all ovarian cancer cases have some degrees of nuclear envelope structural defect due to the loss of lamin A/C (reported here) or emerin protein in a fraction to all of the tumor cell population." (PMID 21439080, 2011). "mRNA for lamin B1 and emerin was found to be generally higher in ovarian cancer and immortalized (HIO) cells than primary human ovarian surface epithelial (HOSE) cells." (PMID 21439080, 2011). "Recently, we found that the nuclear envelope protein emerin is lost in a fraction of ovarian cancer cells." (PMID 21439080, 2011). "For proteins, emerin is often missing or reduced in ovarian cancer lines and noticeably, lamin A/C proteins are generally reduced in ovarian cancer cells." (PMID 21439080, 2011). "Since the nuclear envelope structural protein emerin was found lost in a fraction (38%) of ovarian cancer, we examined if the expression of other nuclear envelope proteins might account for nuclear morphological deformation of emerin-expressing ovarian cancer cells." (PMID 21439080, 2011). "We first tested if known relevant nuclear envelope components in ovarian cancer were deregulated according to cancer nuclear morphological diversification, including LMNA, Lamin B1 and B2, Emerin, nucleoporins NUP88 and NUP1532." (PMID 30254278, 2018). "It appears that emerin mRNA but not protein level is often increased in "immortalized" ovarian epithelial and ovarian cancer cells, and the expression of emerin mRNA and protein levels do not correlate." (PMID 21439080, 2011). "Thus, we conclude that in ovarian cancer cells emerin is lost/reduced at the protein but not the mRNA level; and lamin A and lamin C are reduced both at the mRNA and protein levels." (PMID 21439080, 2011).
prostate tumor (2 papers, 2022 to 2024). "We found that the Emerin pauperization phenotype was twice as frequently detected in metastatic samples than in unmatched primary prostate tumors." (PMID 39218980, 2024). "We also further validated the mRNA and protein expression levels of ANKLE1, EMD, and LEMD2 in human prostate tumor specimens by qPCR, WB, and IHC." (PMID 35650630, 2022). "In addition, we also further validated the mRNA and protein expression levels of ANKLE1, EMD, and LEMD2 in human prostate tumor specimens by qPCR, WB, and IHC." (PMID 35650630, 2022). "Furthermore, we also validated the mRNA and protein expression levels of ANKLE1, EMD, and LEMD2 in human prostate tumor specimens by qPCR, WB, and IHC." (PMID 35650630, 2022).
Arrhythmia (1 paper, 2023). Any cardiac rhythm other than the normal sinus rhythm. "Genes associated with an increased risk of arrhythmias include those encoding nuclear envelope proteins (TMEM43, LMNA, and emerin [EMD]), as well as cytoskeletal and desmosomal proteins (PKP2, DSP, DSC2, and DSG2)." (PMID 37894902, 2023).
Becker muscular dystrophy (1 paper, 2023). Becker muscular dystrophy (BMD) is a neuromuscular disease characterized by progressive muscle wasting and weakness due to degeneration of skeletal, smooth and cardiac muscle. "Group 1, which had both classic emerin and lamin A EDMD mutations, showed an even better match with the Bakay EDMD group which was again very close to LGMD2A but also to DMD, Becker muscular dystrophy (BMD), FSHD and Limb-Girdle muscular dystrophy 2I (LGMD2I)." (PMID 36282542, 2023).
breast tumor (1 paper, 2024). "Ankle2, TMPO, Emerin, and Lemd2 were significantly overexpressed in breast tumor samples, in comparison to adjacent normal tissue." (PMID 38720803, 2024).
cervical cancer (1 paper, 2022). A primary or metastatic malignant neoplasm involving the cervix. "For instance, it has been shown that siRNA-mediated depletion of Lamin A/C or Emerin in cervical cancer cells results in increased ERK phosphorylation and localisation to the nucleus, subsequently enabling activation of downstream transcription factors." (PMID 36205821, 2022). "Similarly, in HeLa cervical cancer cells, the Lem domain protein, Emerin, was shown to relocalise to the centrosomes and microtubules during mitosis." (PMID 36205821, 2022).
colon cancer (1 paper, 2016). "For example, NDRG2, a kinase downstream of the mTOR/SGK pathway and a tumor suppressor that mediates apoptosis, and EMD, a nuclear membrane protein phosphorylated by Src, both preferentially bind HNF4α1 and have been negatively associated with colon cancer." (PMID 27166517, 2016).
Duchenne and Becker muscular dystrophy (1 paper, 2012). Duchenne and Becker muscular dystrophies (DMD and BMD) are neuromuscular diseases characterized by progressive muscle wasting and weakness due to degeneration of skeletal, smooth and cardiac muscle. "In contrast to Duchenne and Becker muscular dystrophy, caused by a mutation of the muscle-stabilizing protein dystrophin, EDMD is associated with an aberration of the inner nuclear membrane proteins emerin or lamin A/C." (PMID 22973525, 2012).
dysferlinopathy (1 paper, 2023). "and emerin, and less frequently in other muscle diseases, such as dysferlinopathy, and this pattern suggests a link between muscle weakness and bone abnormality." (PMID 40757566, 2023).
Dystonia (1 paper, 2014). An abnormally increased muscular tone that causes fixed abnormal postures. "Moreover, LAP1 also interacts with torsinA and emerin, proteins involved in DYT1 dystonia and X-linked Emery-Dreifuss muscular dystrophy disorder, respectively." (PMID 25461922, 2014).
invasive breast carcinoma (1 paper, 2025). A carcinoma that infiltrates the breast parenchyma. "Lower lamin A/C and lamin B1 expression; decreased levels of emerin in invasive breast cancer; downregulation of SUN1, SUN2, and nesprin‐2; upregulation of LBR." (PMID 39866838, 2025).
left ventricular noncompaction (1 paper, 2021). Left ventricular noncompaction (LVNC) is a rare cardiomyopathy characterized anatomically by prominent left ventricular trabeculae and deep intratrabecular recesses causing progressive systolic and diastolic dysfunction, conduction abnormalities, and occasionally thromboembolic events. "Recent research suggests that patients with mutations in the EMD gene can present solely as a cardiac phenotype, termed cardiac emerinopathy, with probable association with left ventricular noncompaction (LVNC) and an increased risk of thromboembolic events." (PMID 34319529, 2021).
limb-girdle muscular dystrophy (1 paper, 2019). Limb-girdle muscular dystrophy (LGMD) is a heterogeneous group of muscular dystrophies characterized by proximal weakness affecting the pelvic and shoulder girdles. "Mutations in nuclear envelopes, emerin (Emd) and lamin A/C (Lmna) genes, cause clinically indistinguishable myopathy called Emery-Dreifuss muscular dystrophy (EDMD) and limb-girdle muscular dystrophy." (PMID 31430335, 2019). "Mutations in EMD and LMNA also cause limb girdle muscular dystrophy." (PMID 31430335, 2019).
mucoepidermoid carcinoma (1 paper, 2025). A carcinoma morphologically characterized the presence of cuboidal mucous cells, goblet-like mucous cells, squamoid cells, cystic changes, and a fibrotic stromal formation. "While direct studies on emerin phosphorylation in mucoepidermoid carcinoma (MEC) are limited, research in other cancers suggests a significant role for emerin in tumor progression." (PMID 40478494, 2025).
muscle disorders (1 paper, 2021). "Given the role of emerin and emerin–prelamin A interplay in muscle physiology and pathology, deeper understanding of emerin fate in HGPS skeletal muscle might provide new insights not only into HGPS pathogenesis, but also on aging‐associated muscle disorders as sarcopenia." (PMID 33393189, 2021).
osteosarcoma (1 paper, 2020). A usually aggressive malignant bone-forming mesenchymal neoplasm, predominantly affecting adolescents and young adults. "As regarding the functional effects dependent on NE protein deregulation in osteosarcoma cells, we described an altered cytoplasm-nuclear shuttling of MKL1 in association with reduced A-type lamin and emerin." (PMID 32069980, 2020). "In conclusion, we described for the first time laminopathic nuclear phenotypes in osteosarcoma cells, providing evidence for an altered lamins and emerin expression and a deregulated nucleoskeleton architecture of this tumor." (PMID 32069980, 2020). "The behavior of these NE components was analyzed in bone tissue sections from controls and patients affected by high and low grade of osteosarcoma in order to assess a correlation between lamins and emerin immunoexpression and their prognostic relevance." (PMID 32069980, 2020). "To provide a prognostic significance of lamins and emerin expression, we assessed NE protein expression of 50 osteosarcoma samples on a tissue microarray (TMA) slide by immunofluorescence staining." (PMID 32069980, 2020). "This study aims characterized the expression of A-type and B-type lamins and emerin in osteosarcoma, revealing a higher percentage of dysmorphic nuclei in osteosarcoma cells in comparison to normal osteoblasts and all the hallmarks of laminopathic features." (PMID 32069980, 2020). "Both lamins and emerin were differentially expressed in osteosarcoma cell lines in comparison to normal osteoblasts and correlated with tumor aggressiveness." (PMID 32069980, 2020). "In accordance with the work of Willer and coauthors, our results clearly showed a reduced nuclear shuttling of MKL1 in those osteosarcoma cells with reduced expression of both A-type lamin and emerin." (PMID 32069980, 2020). "In this study, we deepened the behavior of pivotal components of the nuclear envelope, type A/C and B1 lamins and emerin, in different osteosarcoma cell lines with different malignant aggressiveness, in comparison to human normal osteoblasts." (PMID 32069980, 2020). "In particular, the content of A-type lamin and emerin is reduced in osteosarcoma cells in comparison to normal osteoblasts and this reduction correlate with tumor aggressiveness." (PMID 32069980, 2020). "A global assessment of each nuclear protein in osteosarcoma cell lines revealed an inverse correlation between lamin A/C and emerin immunoexpression and the tumor cell aggressiveness, with a gradual reduction of these NE proteins starting from normal osteoblasts to high aggressive 143B cells." (PMID 32069980, 2020). "In addition to increased nucleoskeletal dysmorphisms, osteosarcoma cell lines have significant alteration of A-type and B-type lamins, as well as of emerin expression in comparison to normal osteoblasts." (PMID 32069980, 2020). "The expression and distribution of lamin A/C, lamin B1 and emerin were investigated by confocal laser scanning microscopy, western blot analysis and RT-PCR, and osteoblasts were considered as reference cells for the osteosarcoma cell lines." (PMID 32069980, 2020). "In contrast, a sample obtained from short-term survival osteosarcoma patient expressed high levels of lamin B1 and no detectable A/C-type lamin and emerin." (PMID 32069980, 2020).
prostate adenocarcinoma (1 paper, 2024). "We found that the EMD gene is very rarely mutated ( < 0.4% of 1607 cases of prostate adenocarcinoma) and that its expression increases slightly with increasing Gleason score." (PMID 39218980, 2024).
type 2 diabetes (1 paper, 2019). "Emerin variant p.D149H, reported as benign with respect to EDMD1, associated significantly with four traits in the Type 2 Diabetes Knowledge Portal: reduced triglycerides and reduced waist circumference, as well as high-impact reductions in LDL cholesterol and cholesterol." (PMID 31024910, 2019).
cancer (18 papers, 2011 to 2025). A tumor composed of atypical neoplastic, often pleomorphic cells that invade other tissues. "Similar findings have been reported in osteosarcoma and breast cancer, where emerin deficiency enhances cancer cell invasiveness." (PMID 41377763, 2025). "Generally, decreased Emerin expression during malignant transformation is associated with nuclear structural defects, increased cancer cell migration and invasion, increased metastatic potential, and unfavorable prognosis." (PMID 39218980, 2024). "The Lem-D proteins, including Ankle2, Lemd2, TMPO, and Emerin, have been shown to be associated with many of the hallmarks of cancer." (PMID 38720803, 2024). "The NE is tightly regulated, and determining the function of emerin in cancer will require studies that can distinguish between the causes and consequences of altered emerin in particular tumor types and disease stages." (PMID 34681951, 2021). "Depletion of emerin causes nuclear shape instability and promotes cancer metastasis." (PMID 41377763, 2025). "Yet, how emerin loss or mutation contributes to the disruption of these crucial pathways in cancer cells remains unclear." (PMID 39866838, 2025). "Reduced emerin levels could thus compromise the stability of cancer cell nuclei, making them more susceptible to deformations and ultimately increasing cell migratory capacity." (PMID 39866838, 2025). "To test whether Emerin-rich MN are genuine cancer-associated structures or are an artifact in some cancer cell lines, we performed immunofluorescence staining of samples of PCa defined as high-risk by the D’Amico classification." (PMID 39218980, 2024). "The identification of the loss of nuclear envelope structural proteins emerin and lamin A/C as the molecular basis of nuclear deformation in cancer cells may provide some explanation." (PMID 21439080, 2011). "However, the mechanisms by which emerin senses these mechanical signals and how its reduction or mutation leads to dysfunctional mechanotransduction in cancer remain unclear." (PMID 39866838, 2025). "In general, decreased Emerin expression during malignant transformation is associated with the nuclear structural defects required for the increased migratory and invasive capacities of cancer cells, leading to increased metastatic potential and unfavorable prognosis." (PMID 39218980, 2024). "Another study using emerin‐null myogenic progenitors and a cancer cell line with low emerin expression (MDA‐231) showed reductions in nuclear area." (PMID 40178931, 2025). "In cancer contexts, the EMD gene presents over a hundred mutations associated with malignancy, many of which influence emerin expression and folding." (PMID 39866838, 2025). "The team conducted experiments using different cell lines and patient samples to understand how Emerin’s misplacement from nuclear envelope to micronuclei can impact cancer cell behavior." (PMID 39218980, 2024). "Of note, it has been demonstrated that mislocalization of emerin in cancer cells leads to nuclear shape instability and it is correlated to a more aggressive phenotype in in vitro and in vivo models." (PMID 35422060, 2022). "It is likely that varying combinations of altered cellular mechanics, cell signaling, and mechanotransduction contribute to the increasingly emerging role of emerin in cancer progression." (PMID 34681951, 2021). "Herein, we discuss the cellular functions of nuclear lamina proteins, with a particular focus on emerin, and how these functions impact cancer progression and metastasis." (PMID 34681951, 2021). "Altered expression of nuclear lamina proteins, including emerin, is found in many cancers and this expression is correlated with better clinical outcomes." (PMID 34681951, 2021). "Emerin was also pointed as a mediator of nuclear shape stability, and in cancer, its destabilization promotes metastasis." (PMID 33490050, 2020).
cancer (continued). "Cancer cells with a delocalized or reduced emerin expression could thus fail to properly control the organization of repressive chromatin, resulting in aberrant gene regulation." (PMID 39866838, 2025). "Knockdown of emerin leads to nuclear shape instability and promotes cancer cell metastasis." (PMID 41377763, 2025). "It was observed that the presence of Emerin-rich micronuclei correlates to more aggressive cancer behavior and could predict worse outcomes." (PMID 39218980, 2024). "Translating these findings into signaling in the context of cancer cells could be important in determining the role of emerin alterations in tumor progression." (PMID 34681951, 2021). "Additionally, proteins from the LINC complex have also been found to be downregulated along with emerin and lamin A/C in some cancers." (PMID 33316938, 2020). "Additionally, a recent study showed that mislocalization of Emerin, a structural protein of the NE, discriminated cancer from healthy tissues and correlated with disease progression in prostate cancer." (PMID 33490050, 2020). "By contrast, human cancer cell lines LNCaP, DU145 and HeLa cells retained similar levels of lamin B1 and emerin in the nuclear bleb compared to the body, suggesting that no rupture had occurred in those blebs." (PMID 41047936, 2025). "Oppositely, human cancer cell lines LNCaP, DU145, and HeLa retained similar levels of lamin B1 and emerin in the nuclear bleb compared to the body." (PMID 40060436, 2025). "When the STAT3 signal, known to be essential for cancer cell proliferation, is activated, cytoplasmic STAT3 protein moves to the nucleus through the nuclear inner membrane where emerin is present." (PMID 34206382, 2021). "For the first time, our paper describes EIF4A1, CLIC1, PRDX6, CLIC4, ENO1, ANXA4, EMD and Ku70 in relation to EEC, although their role is well established in other cancers." (PMID 22415234, 2012). "This suggests that LEM domain proteins or emerin may influence cancer via GCL binding; however, it is unknown the degree that LEM domain proteins regulate cancer-related pathways." (PMID 34681951, 2021).